CENPP (centromere protein P)
Description:
Component of the CENPA-CAD (nucleosome distal) complex, a complex recruited to centromeres which is involved in assembly of kinetochore proteins, mitotic progression and chromosome segregation. May be involved in incorporation of newly synthesized CENPA into centromeres via its interaction with the CENPA-NAC complex.
Synonyms: CENP-P; RP11-19J3.3
Tractability: PROTAC: ubiquitination databases record sites on it.
Gene: Protein-coding gene on chromosome 9 (92,325,953 to 92,620,529, forward strand). Ensembl gene ENSG00000188312.
Subcellular location: Nucleus; Chromosome, centromere
Subcellular location (Human Protein Atlas): Nucleoplasm; Nucleoli
Pathways (Reactome):
Cell Cycle: Amplification of signal from unattached kinetochores via a MAD2 inhibitory signal; Deposition of new CENPA-containing nucleosomes at the centromere; EML4 and NUDC in mitotic spindle formation; Mitotic Prometaphase; Resolution of Sister Chromatid Cohesion; Separation of Sister Chromatids
Signal Transduction: RHO GTPases Activate Formins
Gene Ontology:
Molecular function: protein binding
Biological process: chromosome segregation; CENP-A containing chromatin assembly
Cellular component: inner kinetochore; nucleoplasm; cytosol; nucleus; chromosome, centromeric region
Genetic constraint (gnomAD): Loss-of-function variants: 13 observed, 16.24 expected, observed/expected ratio (o/e) 0.8, 90% interval 0.52 to 1.27. The upper end of that interval is the gene's LOEUF score, 1.27, which puts it in group 5 of 6, group 1 being the genes least tolerant of losing a copy. Missense variants: 222 observed, 214.31 expected, observed/expected ratio (o/e) 1.04, 90% interval 0.93 to 1.16. Synonymous variants: 85 observed, 82.68 expected, observed/expected ratio (o/e) 1.03, 90% interval 0.86 to 1.23.
Homologues: Orthologues: macaque CENPP (95% identical), pig CENPP (76% identical), dog CENPP (73% identical), rabbit CENPP (72% identical), chimpanzee CENPP (69% identical), mouse Cenpp (67% identical), rat Cenpp (67% identical), guinea pig CENPP (65% identical), tropical clawed frog cenpp (40% identical), zebrafish cenpp (35% identical).
Diseases named in the same sentence as CENPP in open-access papers:
CENPP is named in the same sentence as 4 diseases in open-access papers, as found by Europe PMC text mining. Sharing a sentence is not in itself a finding about the gene and the disease. The quoted sentences say what the papers report.
uterine tumor (1 paper, 2017). "CRHR1 has also been reported fused with CENPP, KIA0100, and SPOP, in one breast, cervical, and uterine tumor, respectively." (PMID 28423358, 2017).
tumor (3 papers, 2021 to 2025). "Similarly, the lncRNA LINC01133 may regulate the activity of tumor suppressor pathways by dysregulating ACTL6A, SMARCD2, SMO, PHC3, and CENPP." (PMID 34925461, 2021).
CENPP also shares sentences with these, for which no sentence is quoted: cancer (2 papers); interstitial lung disease (1).